CCL5 (C-C motif chemokine ligand 5)
Diseases named in the same sentence as CCL5 in open-access papers (continued):
Sharing a sentence is not in itself a finding about the gene and the disease.
cutaneous melanoma (15 papers, 2018 to 2024). A primary melanoma arising from atypical melanocytes in the skin. "Patients with high expression of CXCL9, CXCL10, CXCL13, CCL4, and CCL5 in SKCM (Skin cutaneous melanoma) had better overall survival." (PMID 36341437, 2022). "Notably, we found a strong correlation of FLT3LG and CCL5 expression in the case of metastatic human skin cutaneous melanomas (M-SKCM), BRCAs and CESCs." (PMID 33980589, 2021). "In skin cutaneous melanoma (SKCM), cancers with high expression of IL1B, CCL5, CXCL10, and TNFSF15 exhibited better prognoses." (PMID 37980406, 2023). "primarily identified five chemokine members (CCL4, CCL5, CXCL9, CXCL10, CXCL13) as relevant biomarkers in cutaneous melanoma tumorigenesis and progression." (PMID 36713580, 2022). "In summary, this study mainly identified five chemokine members (CXCL9, CXCL10, CXCL13, CCL4, CCL5) associated with SKCM tumorigenesis, progression, prognosis and immune infiltrations, which might help us evaluate several immune-related targets for cutaneous melanoma therapy." (PMID 32508531, 2020). "Moreover, chemotherapy induces intratumoral expression of CCL5, CXCL9, and CXCL10 in cutaneous melanoma, favoring T cell infiltration and tumor control." (PMID 35292660, 2022). "Intestinal microbes may influence the proportion of CD8+ CTLs that infiltrated cutaneous melanomas, and Lachnoclostridium is positively correlated with the expression of infiltrated CD8+ CTLs and the chemokines CXCL9, CXCL10, and CCL5 in cutaneous melanoma tissues." (PMID 38515134, 2024).
lung disease (15 papers, 2006 to 2024). "IP-10, uric acid and CCL5 are associated with lung disease and pulmonary hypertension." (PMID 30840669, 2019). "Other studies have shown that blocking RANTES/CCL5 in vivo significantly increases the titers of respiratory syncytial virus in the lungs of infected mice, and this is associated with reduced T cell recruitment and heightened lung disease." (PMID 21445235, 2011). "Several studies report that inhibition of CCL5 function reduces neutrophil activation, and high CCL5 expression correlates with neutrophil activation in lung disease." (PMID 34745417, 2021). "The HTLV-1 infected lung epithelial cells produce inflammatory chemokines such as CCL2, CCL5, and CCL20, which are all able to contribute to the pathogenesis of HTLV-1 associated pulmonary disorders." (PMID 32231656, 2020). "Only future prospective studies will be able to determine if the levels of CCL2 and CCL5 are predictive of outcomes and if the combined inhibition of these receptor(s)/ligand(s) interactions may lead to an inhibition of progression or even reversal of this lung disease." (PMID 21463523, 2011). "Since CCL3 and CCL5 are involved in the attraction of T cells and memory T cells, high levels of these β-chemokines in HTLV-1 carriers may play a role in developing pulmonary disorders." (PMID 32231656, 2020).
metabolic syndrome (15 papers, 2015 to 2026). A cluster of metabolic risk factors for CARDIOVASCULAR DISEASES and TYPE 2 DIABETES MELLITUS. "The total amount and concentration of CCL5 in the GCF sample from patients with metabolic syndrome and gingivitis was higher than in lean individuals with gingivitis and obese individuals without gingivitis." (PMID 38139161, 2023). "Altered levels of distinct chemokines, like CCL5/RANTES, CXCL12/SDF-1a, CCL7/MCP-3, CCL2/MCP-1, CXCL1/GROa, and the eotaxin family, contribute to the development and/or exacerbation of inflammation, which is a common feature of numerous skin diseases as well as metabolic syndrome." (PMID 42042898, 2026).
multiple myeloma (15 papers, 2014 to 2025). "Kuwahara-Ota and colleagues found that secretion of CCL5/RANTES by myeloma cells is a prerequisite for induction of immunosuppressive myeloid-derived suppressor cells in MM." (PMID 36983384, 2023). "ImiDs were identified as potent inhibitors of immunosuppressive myeloid-derived suppressor cells induction through independent downregulation of CCL5/RANTES in myeloma cells, and downregulation of a receptor for CCL5 chemokine." (PMID 36983384, 2023). "In multiple myeloma, blockage of the CCL5/receptor axis leads to inhibition of osteoclast formation and myeloma cell adhesion to stromal cells." (PMID 36983384, 2023). "BMSC-derived CCL5 together with other chemokines results in enhanced myeloma cell viability and migration." (PMID 30154786, 2018). "Elevated CCL5 levels have also been described in multiple myeloma." (PMID 36983384, 2023). "Tumor-derived miR-146a may induce the activation of Notch1 in BMSCs stimulating them to secrete CCL2 and several cytokines including IL-8, IL-6, CXCL1, IP-10, and CCL5 that enhance myeloma cell viability and migration." (PMID 30154786, 2018). "The secretion of C-C motif chemokine ligand 5 (CCL5) and macrophage migration inhibitory factor (MIF) by myeloma cells is a prerequisite for inducing MDSCs in MM." (PMID 36978204, 2023). "Extracellular vesicles of multiple myeloma (MM) cells can stimulate secretion of cytokines, such as CXCL1, MCP1, IL6, IL-, IP-10, and CCL5 in mesenchymal stromal cells (MSCs) to promote MM cell growth and migration." (PMID 31024564, 2019). "Many studies were published during the last several years on the expression of CCL5 and CCR5 in hematological malignancies, but, only for multiple myeloma (MM) and at least in part for cHL, we have a comprehensive view of the role played by the CCL3-CCL5/CCR5 pair." (PMID 24523569, 2014).
osteoarthritis (15 papers, 2016 to 2025). A noninflammatory degenerative joint disease occurring chiefly in older persons, characterized by degeneration of the articular cartilage, hypertrophy of bone at the margins and changes in the synovial membrane. "In addition, our MR analysis revealed a potential association between the chemokine CCL5, also known as Rantes, and an increased risk of osteoarthritis (OA)." (PMID 36999058, 2023). "In contrast, differences between the synovial fluid levels of CCL2 and CCL5 in equine osteoarthritis (OA)-affected or healthy joints were not reported." (PMID 40496923, 2025). "Monocytes recruited via Ccl2/Ccr2, rather than Ccl5/Ccr5, propagate inflammation and tissue damage in osteoarthritis, thereby representing a promising therapeutic approach." (PMID 34917083, 2021). "Targeting of CCL2 and CCR2 might be a potential treatment of osteoarthritis (OA); in vivo findings from a murine OA model indicated that selective targeting of CCL2/CCR2, rather than CCL5/CCR5, was a viable therapeutic strategy." (PMID 37457301, 2023). "At the same time, their studies showed that the level of CCL2 in the synovial fluid of OA patients was significantly higher than that of ordinary people (CCL2/CCR2, but not CCL5/CCR5, mediates monocyte recruitment, and utilization destruction in osteoarthritis)." (PMID 36619785, 2022). "This activation by RANTES/CCL5 was observed in RASF, but not in osteoarthritis SFs (OASFs)." (PMID 29093715, 2017).
chondrosarcoma (14 papers, 2010 to 2024). A malignant cartilaginous matrix-producing mesenchymal neoplasm arising from the bone and soft tissue. "The autocrine effect of CCL5 in EPC angiogenesis is similar to a previous study showing that CCL5 plays as a paracrine to promote angiogenesis in human chondrosarcoma cells." (PMID 38899522, 2024). "Chemokine CCL5 has been shown to mediate VEGF angiogenesis via inhibition of miR-200b through PI3K/Akt pathway in chondrosarcoma cells." (PMID 29546033, 2018). "Current study showed that CCL5 markedly repressed miR-507 expression in human chondrosarcoma cells in vitro and in vivo." (PMID 27166194, 2016). "Our previous studies have shown that chemokine CCL5 facilitates tumor angiogenesis in human chondrosarcoma." (PMID 27166194, 2016). "Previously, we have demonstrated that CCL5 promotes tumor angiogenesis by VEGF-A production in human chondrosarcoma." (PMID 27166194, 2016). "By down-regulating miR-200b expression through the PI3K/AKT signaling pathway, the chemokine CCL5 (formerly RANTES) promotes VEGF-dependent angiogenesis in human chondrosarcomas." (PMID 27484639, 2016). "We indicated that the expression of CCL5 is highly correlated with tumor stage according the IHC analysis of human chondrosarcoma tissues." (PMID 27166194, 2016). "We reveal that CCL5 increases the production of lymphangiogenic factor VEGF-C by down-regulating miR-507 in chondrosarcoma cells, and thereby promotes tumor lymphangiogenesis in chondrosarcoma microenvironment." (PMID 27166194, 2016). "We previously reported that CCL5 enchances cell migration through activation of matrix metalloproteinase-3 (MMP-3) and promotes VEGF-A-dependent tumor angiogenesis in human chondrosarcoma, implying that CCL5 is involved in the metastasis of chondrosarcoma." (PMID 27166194, 2016). "Herein, we point out that CCL5/CCR5 axis induces VEGF-C-dependent lymphangiogenesis in human chondrosarcoma." (PMID 27166194, 2016). "We next performed miRNome microRNA Profilers QuantiMirTM kit to elucidate miRNA differential expression in CCL5-overexpressed chondrosarcoma cells." (PMID 27166194, 2016). "We tested PI3K phosphorylation after CCL5 treatment; such stimulation of chondrosarcoma cells promoted PI3K phosphorylation time-dependently." (PMID 25301739, 2014). "Earlier we reported CCL5 enhancing chondrosarcoma migration and metastasis via matrix metalloproteinase-3 (MMP-3) up-regulation." (PMID 25301739, 2014). "Stimulation of chondrosarcoma with CCL5 augmented PI3K and Akt phosphorylation, while PI3K and Akt inhibitor or siRNA abolished CCL5-induced VEGF expression and angiogenesis." (PMID 25301739, 2014). "We also gauged hemoglobin content and miR-200b expression to find CCL5 increasing chondrosarcoma-induced angiogenesis but reducing miR-200b expression in vivo; hemoglobin content inversely correlated with miR-200b expression." (PMID 25301739, 2014). "To evaluate CCL5-induced VEGF expression in chondrosarcoma, we applied human recombinant CCL5 to chondrosarcoma cell lines (JJ012 and SW1353 cells) and assessed VEGF expression." (PMID 25301739, 2014). "Taken together, results demonstrate CCL5 promoting VEGF-dependent angiogenesis in human chondrosarcoma cells by down-regulating miR-200b through PI3K/Akt signaling pathway." (PMID 25301739, 2014). "Interestingly, secretion of VEGF induced by CCL5 in chondrosarcoma cell is also via CCR5/AKT/P70S6K axis, albeit through down‐regulation of miR‐200b." (PMID 38899522, 2024). "However interestingly enough, it has been reported that in chondrosarcomas miR-199 family members are negatively regulated by an autocrine feedback loop involving CCL5-VEGFA." (PMID 36418472, 2023). "It has also been reported that the angiogenic actions elicited by CCL5 in chondrosarcoma cells may rely on the down-regulation of miR-199a, which targets JAG-1 to up-regulate VEGF signaling thereby inducing EC differentiation." (PMID 29240722, 2017).
chondrosarcoma (continued). "Chemokine CCL5 has been reported to facilitate angiogenesis and metastasis in chondrosarcoma." (PMID 27166194, 2016). "Importantly, we further demonstrate that CCL5 promotes VEGF-C-mediated tumor lymphangiogenesis by suppressing miR-507 in human chondrosarcoma." (PMID 27166194, 2016). "CCL5 reportedly promotes migration and metastasis in human chondrosarcoma by up-regulating MMP-3." (PMID 25301739, 2014). "In osteosarcoma and chondrosarcoma, CCL5 is proven to expedite migration and metastasis." (PMID 25301739, 2014). "We next correlated among miR-200b, VEGF, and CCL5 in chondrosarcoma." (PMID 25301739, 2014). "We hypothesized miR-200b mediating CCL5-promoted VEGF-dependent angiogenesis in human chondrosarcoma." (PMID 25301739, 2014). "C-C motif chemokine ligand (CCL5), also known as regulated upon activation, normally T-expressed, and presumably secreted (RANTES) has been implicated in downregulation of miR-199a in human chondrosarcoma cells, which promotes VEGF upregulation and angiogenesis." (PMID 29361725, 2018). "We thus hypothesized CCL5 promoting VEGF-dependent angiogenesis in chondrosarcoma." (PMID 25301739, 2014). "Immunohistochemical analysis revealed that overexpression of CCL5 increased the expression of CCL5 and VEGF-C, whereas knockdown of CCL5 decreased the expression of CCL5 and VEGF-C in mouse chondrosarcoma tissues." (PMID 27166194, 2016). "In this study, we showed a clinical correlation between CCL5 and VEGF-C as well as tumor stage in human chondrosarcoma tissues." (PMID 27166194, 2016). "In the current study, we indicate the clinical significance of CCL5 and VEGF-C expression in specimens of chondrosarcoma patients." (PMID 27166194, 2016). "In contract, shRNA-mediated knockdown of CCL5 notably inhibited VEGF-C expression and secretion in human chondrosarcoma cells, and subsequently suppressed migration and tube formation in human LECs." (PMID 27166194, 2016). "However, it is still not well-recognized whether CCL5 increases VEGF-C expression to facilitate tumor-associated lymphangiogenesis in human chondrosarcoma." (PMID 27166194, 2016). "Targeting CCL5 and CCR5 with antagonists will have potential therapeutic usage to restrict the disease progression of many cancers, particularly chondrosarcoma." (PMID 27166194, 2016). "We further demonstrated that CCL5 promoted VEGF-C expression and secretion in human chondrosarcoma cells." (PMID 27166194, 2016). "To validate the effect and targeting miRNA of CCL5 on tumor lymphangiogenesis, we analyzed the expression of CCL5, VEGF-C and miR-507 in tumor tissues which were excised from chondrosarcoma xenograft mice." (PMID 27166194, 2016). "The quantitative data also showed the high positive relationship between the expression of CCL5 and VEGF-C in human chondrosarcoma patients." (PMID 27166194, 2016). "In this study, we investigated the relationship of CCL5 with VEGF-C-mediated lymphangiogenesis, and evaluated the involvement of miRNA in human chondrosarcoma cells." (PMID 27166194, 2016). "To characterize the role of CCL5 in tumor lymphangiogenesis of chondrosarcoma, we first analyzed the expression profile of VEGF-C in specimens of chondrosarcoma patients." (PMID 27166194, 2016). "Chemokine CCL5 (formerly RANTES) of the CC-chemokine family, which plays a critical role in local invasion and distant metastasis in chondrosarcoma, promotes VEGF expression and angiogenesis by downregulating miR-200b." (PMID 27484639, 2016). "Results portend CCL5 acting through PI3K/Akt signal pathway to enhance VEGF expression and angiogenesis in human chondrosarcoma cells." (PMID 25301739, 2014). "CCL5 increased VEGF expression and also promoted chondrosarcoma conditional medium-mediated angiogenesis in vitro and in vivo." (PMID 25301739, 2014). "Indeed, CCL5 stimulated VEGF secretion from EPCs, consistent with previous studies in human chondrosarcoma cells." (PMID 38899522, 2024).
chondrosarcoma (continued). "CCL5 has also been shown to promote VEGFC production and induce lymphangiogenesis via suppressing miR‐507, which binds to 3′UTR of the VEGFC gene, in human chondrosarcoma cells." (PMID 33128283, 2021). "A study on human chondrosarcoma cells revealed that pretreatment with a phosphatidylinositol 3-kinase (PI3K) inhibitor repressed the VEGF production and angiogenesis induced by CCL5/CCR5, suggesting that the PI3K-dependent pathway plays a crucial role in CCL5/CCR5-mediated angiogenesis." (PMID 32194402, 2020). "First, by analyzing gene expression from chondrosarcoma patients, a positive association was found between CCL5 and VEGF mRNA levels, whereas a negative correlation was assessed between CCL5 and miRNA200b expression." (PMID 29240722, 2017). "Moreover, we showed that CCL5 and VEGF-C display a positive correlation in the chondrosarcoma xenograft model." (PMID 27166194, 2016). "Moreover, inhibiting CCL5 dramatically reduced VEGF-C and lymphangiogenesis in the chondrosarcoma xenograft animal model." (PMID 27166194, 2016). "However, the effect of chemokine CCL5 on VEGF-C regulation and lymphangiogenesis in chondrosarcoma has largely remained a mystery." (PMID 27166194, 2016). "In addition, we examined the mRNA expression of CCL5, CCL5 receptors and VEGF-C between normal caritlage and chondrosarcoma." (PMID 27166194, 2016). "Targeting both CCL5 and VEGF-C pathways might serve as the potential therapeutic strategy to block cancer progression and metastasis in chondrosarcoma." (PMID 27166194, 2016). "Pretreatment of chondrosarcoma cells with PI3K inhibitor Ly294002 antagonized increase of VEGF production and angiogenesis by CCL5, as confirmed by siRNA against p85 reducing enhancement of VEGF expression and angiogenesis via CCL5 stimulation." (PMID 25301739, 2014). "We hypothesized this pathway's involvement in CCL5-induced VEGF expression and angiogenesis in chondrosarcoma." (PMID 25301739, 2014). "In addition, CCL5 may play a role in VEGF-C production, as CCL5 has been reported to induce VEGF-C production in human chondrosarcoma cells." (PMID 37461473, 2023). "Also, elevated expression of pro-inflammatory CCL5, CCL3 and their receptor C-C motif chemokine receptor 5 (CCR5), which is a typical surface protein of macrophages and T-cells, has been detected in human chondrosarcoma tissues." (PMID 29361725, 2018). "However, correlation of CCL5 with vascular endothelial growth factor (VEGF) expression and angiogenesis in human chondrosarcoma is still unknown." (PMID 25301739, 2014). "Moreover, in chondrosarcoma patients showed the positive correlation between CCL5 and VEGF; negative correlation between CCL5 and miR-200b." (PMID 25301739, 2014). "Thus, the interaction of CCL5 (RANTES), a product of activated T cells present in bone environment during the tumour process with CCR5 expressed on the cell membrane enhances the migration of chondrosarcoma cells through the increase of MMP-3 production." (PMID 21647363, 2011). "Furthermore, we found that levels of CCL5 and VEGF-C in clinical specimens from patients with chondrosarcoma were correlated with tumor stage, implying that CCL5 may be a potential prognostic indicator for disease progression of human chondrosarcoma." (PMID 27166194, 2016).